WDR18 (WD repeat domain 18)
Description:
Functions as a component of the Five Friends of Methylated CHTOP (5FMC) complex; the 5FMC complex is recruited to ZNF148 by methylated CHTOP, leading to desumoylation of ZNF148 and subsequent transactivation of ZNF148 target genes. Component of the PELP1 complex involved in the nucleolar steps of 28S rRNA maturation and the subsequent nucleoplasmic transit of the pre-60S ribosomal subunit. May play a role during development (By similarity).
Synonyms: Ipi3; R32184_1
Tractability: Small molecule: a structure with a bound ligand is known. PROTAC: ubiquitination databases record sites on it; its protein half-life has been measured.
Gene: Protein-coding gene on chromosome 19 (984,294 to 998,438, forward strand). Ensembl gene ENSG00000065268.
Subcellular location: Nucleus, nucleolus; Nucleus, nucleoplasm; Cytoplasm; Dynein axonemal particle
Subcellular location (Human Protein Atlas): Nucleoplasm
Pathways (Reactome):
Metabolism of RNA: Major pathway of rRNA processing in the nucleolus and cytosol
Gene Ontology:
Molecular function: protein binding
Biological process: cleavage in ITS2 between 5.8S rRNA and LSU-rRNA of tricistronic rRNA transcript (SSU-rRNA, 5.8S rRNA, LSU-rRNA); DNA-templated DNA replication; rRNA processing
Cellular component: nucleoplasm; nucleus; rixosome complex; cytoplasm; dynein axonemal particle; nuclear pre-replicative complex; nucleolus
Genetic constraint (gnomAD): Loss-of-function variants: 33 observed, 36.12 expected, observed/expected ratio (o/e) 0.91, 90% interval 0.69 to 1.22. The synonymous counts are far from expectation, so gnomAD's model fits this gene poorly and the ratio says little. Missense variants: 653 observed, 520.68 expected, observed/expected ratio (o/e) 1.25, 90% interval 1.17 to 1.34. Synonymous variants: 315 observed, 230.49 expected, observed/expected ratio (o/e) 1.37, 90% interval 1.25 to 1.5.
Homologues: Orthologues: chimpanzee WDR18 (99% identical), pig WDR18 (92% identical), macaque WDR18 (91% identical), dog WDR18 (91% identical), guinea pig WDR18 (85% identical), mouse Wdr18 (83% identical), rat Wdr18 (83% identical), tropical clawed frog wdr18 (64% identical), zebrafish wdr18 (61% identical), Drosophila melanogaster CG14805 (31% identical), Caenorhabditis elegans pro-1 (22% identical).
Diseases named in the same sentence as WDR18 in open-access papers:
WDR18 is named in the same sentence as 6 diseases in open-access papers, as found by Europe PMC text mining. Sharing a sentence is not in itself a finding about the gene and the disease. The quoted sentences say what the papers report.
dementia (1 paper, 2025). Loss of intellectual abilities interfering with an individual's social and occupational functions. "WDR18 has not been linked to dementia relevant outcomes but is involved with many cellular processes including cell cycle progression, signal transduction, apoptosis, and gene regulation." (PMID 40708016, 2025).
cancer (2 papers, 2021 to 2024). A tumor composed of atypical neoplastic, often pleomorphic cells that invade other tissues. "Interestingly, other components of the Rix1 complex (WDR18 and TEX10) are also found overexpressed in cancer, indicating that the function of this complex is required to support high rates of ribosome biogenesis in cancer." (PMID 38633862, 2024).
tumor (1 paper, 2020). "LINC00346 enhanced the expression of WD Repeat Domain 18 (WDR18) by virtue of competitively binding to miR-542-3p, a downregulated tumor suppressor in HCC cells." (PMID 33299889, 2020).
WDR18 also shares sentences with these, for which no sentence is quoted: melanoma (2 papers); meningioma (1); viral infection (1).